RNVU1-4 (RNA, variant U1 small nuclear 4)
Synonyms: vU1.4; RNU1-102; vU1.5; RNU1-50; RNVU1-5
Gene: Small nuclear RNA gene on chromosome 1 (120,942,600 to 120,942,763, forward strand). Ensembl gene ENSG00000277610.
Gene Ontology:
Molecular function: pre-mRNA 5'-splice site binding
Biological process: mRNA 5'-splice site recognition
Cellular component: U1 snRNP
Homologues: Orthologues: dog U1 (72% identical), rabbit U1 (62% identical). Paralogues in human: RNVU1-30 (96% identical), RNVU1-3 (91% identical), RNVU1-7 (80% identical), RNU1-1 (80% identical), RNU1-2 (80% identical), RNU1-27P (80% identical), RNU1-28P (80% identical), RNU1-3 (80% identical), RNU1-4 (80% identical), RNVU1-18 (80% identical), RNVU1-29 (80% identical), RNVU1-2A (80% identical), and 134 more.